EGFR (epidermal growth factor receptor)
Diseases named in the same sentence as EGFR in open-access papers (continued):
Sharing a sentence is not in itself a finding about the gene and the disease.
tumor (continued). "Tumor cells pretreated with anti-epidermal growth factor receptor inhibitors showed the increased sensitivity toward NK cell-mediated antibody-dependent cellular cytotoxicity." (PMID 33679883, 2021). "Altogether, these observations support that EGFR is a relevant target due to its expression in tumor cells and its absence in stroma." (PMID 36405501, 2021). "Our data demonstrated that Notch signaling plays a critical role in maintaining MEC stem-like cells and MEC tumor growth and revealed that a novel approach of targeting Notch and EGFR signaling serves as a potential effective anti-MEC treatment." (PMID 33473104, 2021). "It was shown that cigarette smoking (CS) is associated with worse prognosis in OSCC patients and overexpression of EGFR in tumor tissue." (PMID 34298758, 2021). "High tumor EGFR expression in HNSCC patients correlates with elevated local recurrence and inferior disease-free survival." (PMID 33718186, 2021). "In the case of NSCLC, research indicates stimulation of tumor growth through the expression of ER forms that interact with the epidermal growth factor receptor (EGFR)." (PMID 33466597, 2021). "Targeting AXL were shown to sensitize tumours to various types of therapies, including DNA damaging agents, EGFR, VEGFR, HDAC, G2/M checkpoint, and immune checkpoint inhibitors." (PMID 34638349, 2021). "Gauthier and co-workers developed a multifunctional antibody (NKp46 specific) targeting CD19, CD20, or EGFR as tumor antigens and triggering tumor killing by NK cells." (PMID 33763348, 2021). "Although osimertinib response was not different between the two groups, we focused on the attenuation of tumor cells by EGFR-TKIs immediately before the administration of osimertinib to clarify the correlation between T790M ratio and osimertinib response." (PMID 33953280, 2021). "As a result, these tri-specific PEG-PLGA NPs demonstrated effective NK cell activation by the spatiotemporal co-activation of CD16 and 4-1BB stimulatory molecules on NK cells and promoted NK cell recruitment to EGFR-positive tumor cells." (PMID 34930494, 2021). "Instead, Lnc-EGFR is expressed in T regulatory cells (Tregs), correlating positively with tumor size and EGFR expression and negatively with IFN-γ levels." (PMID 34071216, 2021). "One of the genes picked up for sorafenib was EGFR and among the genes for topotecan was a tumor suppressing genes ST14 (matriptase)." (PMID 33413081, 2021). "A phase I clinical trial (NCT02369198) using an epidermal growth factor receptor (EGFR) antibody-coated bacterial-derived minicell system loaded with miR-16 mimic (MesomiR-1) showed an effective inhibition of tumor growth." (PMID 34944942, 2021). "The highest benefit was observed in patients with RAS, BRAF, and EGFR wild-type tumor assessed by basal plasma circulating tumor DNA (ctDNA) analysis." (PMID 34830870, 2021). "Of the 1117 patients included, 420 (38%) had KRAS mut tumours, 142 (13%) had EGFR mut tumours, 12 (1%) had ALK rearranged tumours, and 3 (0.3%) patients had ROS1 rearranged tumours." (PMID 34503114, 2021). "In the current study, exogenous IL-26 induced dephosphorylation of EphA3 in TNBC, followed by phosphorylation of AKT and JNK leading to suppression of ER stress signaling, resulting in enhanced tumor growth of EGFR-TKI-resistant TNBC." (PMID 34021125, 2021). "We have shown broad cross-reactivity of 806 CAR T cells to EGFR mutant proteins resulting in enhanced anti-GBM tumor killing, along with a low on-target, off-tumor effect against both astrocytes and keratinocytes that express wild-type EGFR." (PMID 34568006, 2021). "As the upstream gene of the ERK/AKT pathway, EGFR is closely related to the proliferation, invasion, and migration of tumor cells." (PMID 34539892, 2021). "The influence of EGFR in the pathogenesis of different cancer types has been widely studied, being used as a biomarker in the profiling of different tumor types." (PMID 33916986, 2021).
tumor (continued). "Erlotinib displays anti-tumor activities more effectively on tumor growth inhibition when administered in the early-light than in the early-dark phase of the circadian rhythm when EGFR activities and its downstream factors increase (Li XM." (PMID 34966277, 2021). "Nevertheless, the authors claimed that there was a substantial discordance (16.2%) on EGFR status between the primary tumor and their corresponding metastasis." (PMID 34199799, 2021). "It has been found that some tumor-specific alternative splicing target antigens, such as EGFR alternative splicing, only exist in some tumor cells." (PMID 34249669, 2021). "We then examined the change in SGLT1 expression in human NSCLC tumor tissues after the development of acquired resistance to EGFR TKIs." (PMID 34155348, 2021). "The application of AXLi-enhanced cytotoxic and anti-tumour effects of compounds in vitro target RTKs, EGFR, HER2, PDGFR, cMET, VEGFR, and cKIT." (PMID 34638349, 2021). "EGFR is a receptor that promotes tumor occurrence and development; its expression in tumor tissues is higher than that in adjacent and normal tissues." (PMID 33718153, 2021). "This indicates CAR-mediated killing of FR-α-positive tumor cells in addition to BiTE-mediated killing via EGFR targeting." (PMID 33863363, 2021). "After 4 h of intravenous injection, EGFR-targeted QD-Ab probe specifically accumulated in tumor tissue." (PMID 34322025, 2021). "Numerous published reports have shown the pathogenetic role of the epidermal growth factor receptor (EGFR) in tumor initiation and progression." (PMID 34959401, 2021). "In order to solve the lack of specific tumor-targeting capability, anti-EGFR Affibody (ZEGFR:1907)-based Ag2S QD (ZEGFR:1907-Ag2S QDs) nanoprobes have been successfully synthesized and used for targeted photoacoustic imaging of EGFR-overexpressed tumor." (PMID 34322025, 2021). "The rationale behind this study is based on the fact that VEGF expression levels change dynamically during anti-tumor therapy, and EGFR-TKI resistance is often accompanied by increased levels of VEGF." (PMID 35046801, 2021). "Epidermal growth factor (EGF) is the ligand of EGF receptor (EGFR) overexpressed on the surface of various tumor cells." (PMID 34915901, 2021). "By means of Pearson’s rank correlation test, we found a significant correlation between growth inhibition by AcoA and the EGFR expression levels in the NCI-60 tumor cells." (PMID 34025398, 2021). "Due to the proliferative nature of the tumor, controlled mainly by key growth factors and their receptors, EGFR can activate pathways necessary for the development of GBM cancer cells." (PMID 34210107, 2021). "Thought to act as a downstream mediator of numerous oncogenic drivers, such as KRAS, EGFR, or mutated PTEN, PI3K-AKT-mTOR pathway signalling controls tumour development and regulates the cellular composition of the TME29,35,36." (PMID 34381028, 2021). "N-myc downstream-regulated gene 1 (NDRG1) is a key regulator that interacts with many classic tumor signaling pathways, including some molecules downstream of the epidermal growth factor receptor (EGFR)." (PMID 34385595, 2021). "Another study showed that in head and neck cancer, the anti-EGFR mAb cetuximab combined with an anti-CD137 agonist antibody leads to tumor regression and prolonged survival." (PMID 34572847, 2021). "EGFR has an important role in initiating the signalling that directs the behaviour of epithelial cells and tumours of epithelial origin." (PMID 34298667, 2021). "Cetuximab, an EGFR-targeted drug that has entered clinical trials, plays an anti-tumor role by binding to the extracellular domain of the EGFR." (PMID 34578147, 2021). "Our conclusion that anti-EGFR mAb achieved its best value in patients with pan-RAS WT left-sided tumor is likely generalizable across different countries." (PMID 34012917, 2021). "Due to this central role in proliferation, survival and angiogenesis, EGFR overexpression confers a major advantage to tumour cells." (PMID 34829955, 2021).
tumor (continued). "In one study, high levels of cytokines (IL-2, IL-4, IL-10, TNF-α, and interferon [IFN]-γ) were released 24 h after in vitro co-incubation of EGFR-positive tumor cells with anti-EGFR CAR-T cells." (PMID 33025047, 2021). "Evidence suggests that EGFR overexpression leads to tumor cell survival, proliferation, invasion and metastasis." (PMID 34689164, 2021). "In this study, SLC1A5 inhibition not only enhanced the anti-tumor effect of Almonertinib on EGFR mutant cell lines (H1975), but greatly improved the anti-tumor effect of Almonertinib on EGFR WT cell lines (A549)." (PMID 34054543, 2021). "The KRAS/NRAS/BRAF are the downstream effectors of the EGFR signal pathway involved in tumor cell proliferation, differentiation, and invasion." (PMID 34395262, 2021). "Bystander T cells occupy the tumor space, where T cells are reportedly distributed spatially; thus, patients with EGFR 19del would have higher clonality, resulting in poorer immune treatment efficacy." (PMID 33777727, 2021). "In an effort to further shorten the staining protocol, DDSI contrast following each minute of washing was evaluated in the highly EGFR expressing A431 and mid-level EGFR expressing AsPC-1 tumors (n = 6 tumor samples per condition)." (PMID 33882909, 2021). "Some researchers had mentioned in their study that EGFR functioned in tumor genesis, and also played an important role in tumor processing." (PMID 34589430, 2021). "Next, we examined the distribution profile of 18F-FDG-accumulating hypoxic cells by combining micro-autoradiography with immunohistochemistry for EGFR, an A431 cell-derived tumor cell marker, and pimonidazole in the same tumor slices." (PMID 33994540, 2021). "Because of its importance for tumor development and progression, the EGFR has long been considered as a promising target molecule for tumor therapy." (PMID 34830971, 2021). "MMP14 activity also triggers the proteolytic processing and activation of Heparin-Binding EGF-like growth factor (HB-EGF), which stimulates the EGFR signaling pathway and increases tumor proliferation and growth." (PMID 34976811, 2021). "Preclinical studies have shown the superior anti-tumour activity of tarloxotinib compared to various clinical-stage EGFR-TKIs." (PMID 33923305, 2021). "Three compounds, 2b, 2f, and 2i, exhibited the most potent activity (GI50: 4.03, 2.94, and 2.96 μM, respectively) and the best tumor selectivity (ratio: more than 7.44) against the MDA-MB-468 cell line as an EGFR-overexpressed TNBC." (PMID 34681198, 2021). "We identify Areg as a direct target of TTP in keratinocytes and show that EGFR signaling potentially contributed to exacerbated tumor formation." (PMID 33497366, 2021). "The applied combination interfered with tumor cell metabolism, inhibited the EGFR signaling pathway and activated the AMPK signaling pathway (AMP-activated protein kinase)." (PMID 34805097, 2021). "Overexpression of IL6 reduces methylation of the EGFR promoter and enhances EGFR expression, leading to tumor growth promotion." (PMID 33579265, 2021). "The AFs of sensitizing EGFR mutations measured by ddPCR and NGS at baseline were weakly to moderately well-correlated with baseline tumor volume (Spearman ρ = 0.36 with p = 0.074 for ddPCR and Spearman ρ = 0.45 with p = 0.026 for NGS)." (PMID 34283064, 2021). "One of the key enrolment criteria into the AURA3 trial was a centrally confirmed T790M-positive tumour tissue after first-line EGFR-TKI therapy." (PMID 33741979, 2021). "Preclinical studies showed promise with murine xenograft models treated with chimeric anti-EGFR monoclonal antibody, cetuximab, demonstrating attenuation of tumor growth." (PMID 34062753, 2021). "Wild-type KRAS or low EGFR expressing tumor cells are therefore likely to exhibit increased resistance to lysis by reovirus or cetuximab-mediated ADCC." (PMID 33933132, 2021).
tumor (continued). "In this work, we have engineered ultralong CDR-H3 common light chain bispecific antibodies targeting Epidermal Growth Factor Receptor (EGFR) on tumor cells as well as Natural Cytotoxicity Receptor NKp30 on Natural Killer (NK) cells." (PMID 35087526, 2021). "The epidermal growth factor receptor (EGFR) plays an integral role in tumor biology and its expression has been correlated with more aggressive disease." (PMID 34298761, 2021). "After overexpression of miR-34a, cell proliferation was inhibited, and the expression level of EGFR was significantly decreased, which indicated that miR-34a inhibited the growth of mouse tumor." (PMID 34696703, 2021). "The metalloprotease, a disintegrin and metalloproteinase 17 (ADAM17), can activate ligands of the epidermal growth factor receptor (EGFR) and contribute to tumor progression." (PMID 34224305, 2021). "The expression of EGFR ligands in primary tumours is potentially related to anti-EGFR therapy efficiency." (PMID 34663410, 2021). "SPINK1 modulated tumor malignancies and induced the activation of the downstream signaling of epidermal growth factor receptor (EGFR) in cancer cells, due to the structural similarity with epidermal growth factor (EGF)." (PMID 33916984, 2021). "The heterogeneity in time-to-recurrence and OS observed within the ADJUVANT cohorts suggested high inter-tumor molecular heterogeneity in early-stage EGFR-mutant NSCLC11, necessitating additional predictive biomarkers to redefine personalized adjuvant therapy." (PMID 34750392, 2021). "Delivery of lncRNA LINC00520 in cutaneous squamous cell carcinoma inhibited phosphoinositide 3-kinases/ protein kinase B signaling pathway by targeting the EGFR inhibition which in turn suppressed tumor growth, proliferation and migration." (PMID 34677212, 2021). "Specifically, ADAM17 is known to have a major role in activating most ligands of EGFR, such as amphiregulin, heparin-binding epidermal growth factor and epigen, representing a crucial pathway for tumor progression." (PMID 34224305, 2021). "By evaluating CD8 T-cell infiltration in the induced tumours, we can confirm the effect of CD8 T-cell exclusion driven by EGFR oncogenic mutation signals." (PMID 35052732, 2021). "First analysis of this clinical trial reported stable disease in 6/11 patients (55%) in the cohort of EGFR exon 20 insertions and tumor reduction by RECIST in 4/9 evaluable patients (44%) in the cohort of HER2 activating mutation." (PMID 33710795, 2021). "The EGFR-L1 peptide was selected from the computational screening of a large peptide library and shown to target EGFR in vitro (using H1299 cells overexpressing EGFR) and in vivo (using H1299 tumor-bearing mice)." (PMID 33670650, 2021). "Overall survival was significantly correlated with ctDNA status (p < 0.001), advanced M stage above M1a (p < 0.001), the site of tumor tissue obtained for EGFR analysis (p = 0.006), and the size of the largest tumor deposit 30 mm or above (p = 0.024)." (PMID 34574036, 2021). "Here we investigate the influence of the binding affinity of proteins on tumor localization by using four repebodies having different affinities to EGFR." (PMID 33615202, 2021). "Patients with EGFR mutations have lower tumor mutation burden (TMB) levels and reduced tumor-infiltrating lymphocytes compared with other patients; they thus have lower immunogenicity and antitumor immunity." (PMID 34373555, 2021). "Because EGFR was highly expressed in our NPC PDX cell line, we examined the role of EGFR in NPC tumor-related function." (PMID 34204797, 2021).
tumor (continued). "Src plays a major role in cancer cell growth and survival, and thereby tumor angiogenesis, by acting as an initial prompt in molecular signaling pathways that transmit signals from EGFR to their downstream targets to promote tumor invasion and metastasis." (PMID 33925065, 2021). "EGFL7 controls intercellular and cell–matrix communication, which are key features of tumor progression and metastasis, by hijacking the receptor tyrosine kinase epidermal growth factor receptor (EGFR), integrin, and Notch signaling pathways." (PMID 33804387, 2021). "Of the five patient tumors with identified EGFR amplification, all showed membranous EGFR protein expression (three showed 3+ staining and two showed 2+ staining in >10% of tumor cells)." (PMID 34912708, 2021). "We report our experience of the PLUREX study in which we tested the sensitivity of EGFR mutational screening on different cfDNA sources (plasma, urine and EBC) in order to obtain the best surrogate to the tumor tissue." (PMID 34771566, 2021). "Among Japanese patients in LUX-Lung 3, prolonged progression-free survival (PFS) and improved overall survival (OS) in patients with EGFR Del19-positive tumours was confirmed for afatinib versus platinum-based chemotherapy." (PMID 33648453, 2021). "Exemplarily, mRNA was applied in one study to transiently force T cells to express an epidermal growth factor receptor (EGFR)-specific CAR to eradicate EGFR-expressing tumor cells." (PMID 33722265, 2021). "EGFR inhibition reduces UV-induced erythema, hyperplasia, lymphocyte infiltration, cytokine production, and tumor size." (PMID 34553848, 2021). "In this regard, it is interesting to note that many of the circulating trans-differentiated tumor cells overexpress EGFR, the activation of which is known to strongly support epithelial cell survival." (PMID 34948338, 2021). "Under hypoxic stress, epidermal growth factor receptor (EGFR) suppresses the maturation of specific tumor-suppressor miRNAs by phosphorylation of argonaute 2 (AGO2)." (PMID 33898432, 2021). "The 89Zr-EGFR-CXCR5-CAR-T cells showed trafficking to the A549-CXCL13 tumor 72 h post-infusion, whereas the 89Zr-EGFR-CAR-T cells and 89Zr-mock control T cells were barely detectable." (PMID 34553036, 2021). "In patients with GBM, although CAR-T cells targeting EGFRvIII decreased the number of EGFRvIII-expressing tumor cells, subsequent analysis of surgical samples showed a high level of wild-type EGFR in the tumor site." (PMID 34039409, 2021). "In this study, the combination of osimertinib and dasatinib has shown anti-tumor activity in patients with EGFR-mutant NSCLC in the front-line setting, but the treatment was limited by chronic toxicities mainly attributed to dasatinib." (PMID 34568058, 2021). "EGFR promotes tumour cell division and tumour growth and, due to its overexpression, it serves as a promising target for targeted therapy." (PMID 33737524, 2021). "In summary, our study sheds light on the mechanisms of cancer escape from anti-tumor immunity via increased PD-L1 protein levels downstream of EGFR overexpression and overactivation in cancer." (PMID 33879767, 2021). "A total of 310 cases had progressive disease, defined as an increase in tumor size or number of metastases as confirmed by the radiological review of the CT or PET-CT scans, and 197 (63.5%) cases showed EGFR mutation in ctDNA analysis." (PMID 34574036, 2021). "Firstly, FBXL2-mediated inhibition of cell proliferation and tumor growth can be completely rescued by restoration of EGFR expression." (PMID 34635651, 2021). "In summary, our study demonstrated a critical role of Notch signaling in maintaining MEC stem-like cells and tumor growth and revealed that the approach of co-targeting Notch and EGFR signaling is a potential effective anti-MEC treatment." (PMID 33473104, 2021). "An EGFR-targeted nanobody linked to a polymeric micelle (PM), nanobody modified DOX-PM, inhibited tumor growth and prolonged survival." (PMID 34207137, 2021).